LAIR1 (leukocyte associated immunoglobulin like receptor 1)
Diseases named in the same sentence as LAIR1 in open-access papers (continued):
Sharing a sentence is not in itself a finding about the gene and the disease.
tumor (continued). "Treatment with a commercially available anti–mouse LAIR1 antibody alone or in combination with anti–PD-1 antibody or 8R70CAR T cells reduced tumor burden and extended mOS in murine GBM and lung carcinoma models." (PMID 40829176, 2025). "Five doses of anti-Lair1 antibody (200 μg/dose) were administered after tumor establishment followed by 5 doses of anti-Lair1 antibody (200ug/dose) and 1 dose of mouse CD70CAR T cells." (PMID 40591413, 2025). "We uncovered a tumor immunosuppressive pathway involving LAIR1 and developed therapeutic approaches, including antibody blockade and a new signal-delivering CAR to reverse its effect." (PMID 40591413, 2025). "Regarding neoplasia of the hematopoietic and lymphoid system, we have recently described the role of LAIR1 in the pathogenesis of follicular lymphoma and diffuse large B-cell lymphoma." (PMID 41153806, 2025). "Overall, the direct effects of LAIR1 cross-linking on solid tumor cells should be tested to better support the notion that LAIR1 triggers a positive signal in some tumor cell lines." (PMID 40563506, 2025). "This new CAR design combines targeting of CD70 on tumors, enhancement of T cell tumor trafficking via expression of the IL-8 receptor, and inhibition of LAIR1 by secreting soluble LAIR2 to remodel the immunosuppressive TME." (PMID 40591413, 2025). "We observed that Lair1–/– tumor-bearing mice had a more robust antitumor response than did their Lair1+/+ counterparts." (PMID 40591413, 2025). "Remarkably, through 3D imaging reconstruction, we visualized increased collagen IV accumulation in Lair1+/+ tumors, characterized by a dense “collagen web” structure that enveloped tumor cells and obscured tumor nuclei." (PMID 40591413, 2025). "The results showed that CAR T cells and anti-Lair1 antibody treatment alone inhibited tumor growth, and a synergistic antitumor effect was seen when anti-Lair1 antibody was combined with the CAR T cells." (PMID 40591413, 2025). "Nevertheless, our current knowledge regarding the roles of distinct myeloid cell subsets in tumor progression and the effect of LAIR1 on M2-like MΦ functions and response to therapeutic drugs remains limited." (PMID 40591413, 2025). "Both transmembrane and extracellular collagens produced by tumor and stromal cells can engage leukocyte-associated immunoglobulin-like receptor-1 (LAIR-1, CD305), activating inhibitory signaling pathways." (PMID 41303704, 2025). "Hereafter, we will report and discuss the experimental evidence supporting the possible use of LAIR1 as a target for tumor therapy in both hematological and solid neoplasia." (PMID 40563506, 2025). "In the TME, it is conceivable that PD1 interacts with PDL1 on tumor cells while LAIR1 binds to collagen in the stroma." (PMID 40563506, 2025). "The data of the Lair1–/– experiments established a solid foundation to untangle the role of LAIR1 in tumor immunosuppression and devise potential therapeutic strategies." (PMID 40591413, 2025). "The presence of soluble LAIR1 was evidenced in tissue-exudative extracellular vesicles (Te-EVs) in RCC regions compared to the next non-tumor regions." (PMID 40563506, 2025). "The expression of LAIR1 on tumor cells should be considered together with the expression of other inhibitory receptors of immune cell functions." (PMID 40563506, 2025). "LAIR-1 was identified as having an inhibitory effect on the tumor cells’ invasion ability, negatively affecting BC lesions’ elasticity value, which is an indication of cancer cells’ active growth and proliferation." (PMID 40806280, 2025). "In the tumor microenvironment, MMP9 degrades type I collagen, releasing fragments that engage the inhibitory receptor leukocyte-associated immunoglobulin-like receptor-1 (Lair-1) on T cells and attenuate TCR signaling." (PMID 41306770, 2025).
tumor (continued). "A systematic analysis of the expression of each isoform on healthy and pathologic cells can shed some light on the biological significance of LAIR1 in physiological functions and in several inflammatory and neoplastic diseases." (PMID 40563506, 2025). "Summarizing our findings, we have demonstrated a mechanism involving LAIR1+ M2-like MΦ/TAMs in tumor immunosuppression and progression." (PMID 40591413, 2025). "The results demonstrated that anti-Lair1 antibody treatment more effectively inhibited tumor growth than did the IgG control, and it surpassed aPD-1 in tumor shrinkage at later time points." (PMID 40591413, 2025). "Because collagen is both the ligand of LAIR1 and a contributor to immunotherapy resistance, collagen content was evaluated in tumor models treated with anti-LAIR approaches." (PMID 40829176, 2025). "Next, we performed IF staining of GBM specimens, attempting to determine if LAIR1 was on tumor-infiltrating MΦ or resident microglia using CD45 and transmembrane protein 119 (Tmem119), a microglia marker." (PMID 40591413, 2025). "Although the presence of LAIR1 and its inhibitory role on immune cells has been documented, its function during tumorigenesis and tumor progression remains contradictory." (PMID 40563506, 2025). "Future research is necessary to understand how LAIR1 contributes to M2-like MΦ-mediated immunosuppression/tumor progression and to develop innovative therapeutic strategies targeting LAIR1 signaling." (PMID 40591413, 2025). "The representative images captured from the videos 60 hours after coculturing showed more CAR T cell–tumor interactions by the anti-Lair1 antibody than by IgG." (PMID 40591413, 2025). "In this issue of JCI, Tao and colleagues tested multiple approaches targeting LAIR1 signaling in several different in vitro human and in vivo mouse tumor models." (PMID 40829176, 2025). "The relevance of LAIR1 in the tumor microenvironment will be considered in a specific chapter, together with the possible ways of regulating the LAIR1-mediated immune escape of tumors." (PMID 40563506, 2025). "(2021) showed that genetic ablation of LAIR-1 in the myeloid lineage results in increased tumour burden in a B16-F10 metastasis model." (PMID 38236251, 2024). "Studies in mice showed that LAIR1 controls homeostatic and anti-tumor functions of monocytes and interstitial macrophages in the lungs via stromal sensing." (PMID 38832018, 2024). "Collagen deposition inhibits NK cells by inhibiting LAIR1 signaling and promotes tumor colonisation." (PMID 38690275, 2024). "Leukocyte-associated Ig-like receptor-1 (LAIR-1), also known as CD305, is another inhibitory receptor that can be exploited by viruses and tumor cells to evade the immune response." (PMID 39065812, 2024). "Horn and colleagues assessed the combined inhibition of TGF-β, PD-L1, and LAIR-1 signals in a cancer mouse tumor model." (PMID 38690275, 2024). "While LAIR-1 is known to be expressed on CD8+ infiltrating T cells in the tumour microenvironment (TME), it is also highly expressed on cells of the myeloid lineage, such as monocytes and macrophages." (PMID 38236251, 2024). "Of interest, LAIR1 blockade by antagonist antibodies inhibited tumor development in a humanized mouse model by affecting, among others, the recruitment of pro-tumorigenic pDCs." (PMID 38504978, 2024). "Combined with TCGA and CGGA cohort, TRIM56 was most closely correlated with LAIR1, CD44, PDCD1LG2 and CD274, and oncoplots were used to display the tumor mutation gene microlandscape of TRIM56 high expression group and low expression group." (PMID 38348047, 2024). "GrB+ B cells from tumor samples exhibited slightly higher expression levels of LAIR1 and NR4A1 but a lower level of CD69 expression." (PMID 38386050, 2024). "Tumour outgrowth in the mice treated with isotype was similar between Lair1+/+ and Lair1−/− mice (top- and bottom-left)." (PMID 38236251, 2024).
tumor (continued). "We observed that CD14+, CD68+, and CD163+ monocytes and CK+ tumor cells predominantly expressed LAIR-1 more than other cell types." (PMID 36960400, 2023). "A similar trend for the mean LAIR-1 expression of both tumor (P = 0.06) and stroma (P = 0.09) was observed in the validation cohort." (PMID 36960400, 2023). "The presence of LAIR-1, a cell surface receptor found on different immune cells, contributes to the intricate immune regulation occurring within the tumor microenvironment." (PMID 38332915, 2023). "Elevated collagen can promote CD8+ T cell exhaustion through Leukocyte associated immunoglobulin like receptor 1 (LAIR1) receptors and anti-PD-1 treatment, and a blockade of LAIR1 significantly reduces tumour growth and metastasis." (PMID 37949863, 2023). "In the tumor microenvironment, regarding LAIR‐1 cross‐linking with its collagen or other ligands, it leads to a decrease in immune activity, along with a decline in T‐cell function, thereby worsening the overall survival." (PMID 37647449, 2023). "Several studies show that disrupting LAIR-1 interactions with collagens results in enhanced tumor immunity." (PMID 37662958, 2023). "Across these studies, it was demonstrated that therapeutic targeting of the LAIR-1 pathway in tumor models promoted the activation and function of T cells, NK cells, macrophages, and DCs." (PMID 37662958, 2023). "The confirmation of LAIR-1 on tumor cells suggests further study of mechanisms of LAIR-1 expression on tumor cells, the role of tumor cell-intrinsic LAIR-1 signaling, and the role of LAIR-1 adhesion to tumor collagens is warranted." (PMID 36960400, 2023). "When collagen XVII fibers present in the ECM surrounding the tumor binds to LAIR-1, the signal transduction results in inhibitory signals that cause T cell exhaustion and impairment of NK cell, monocyte and dendritic cell activation and proper function." (PMID 37284199, 2023). "A recent tumor study in mice found that LAIR‐2‐Fc recombinant protein inhibits the binding of LAIR‐1 and collagen by blocking the PD‐1/PD‐L1 checkpoint, so as to achieve an anti‐tumor effect." (PMID 35702880, 2023). "Understanding the relative abundance of tumor and stromal cells where LAIR-1 is expressed can be a predictive feature to guide therapeutic decision-making through composite assessment of biomarkers and/or treatment regimens." (PMID 36960400, 2023). "Taken together, our results indicated that LAIR-1 is highly expressed in LUAD subtype, and that high level of LAIR-1 expression is associated with poor survival, suggesting LAIR-1 in tumor can be an independent prognostic marker for patients with LUAD subtype." (PMID 36960400, 2023). "The notion that LAIR-1 is highly expressed on tumor cells requires further evaluation on tumor cell intrinsic function of LAIR-1 in the context of therapeutic blockade of tumor LAIR-1 versus immune LAIR-1." (PMID 36960400, 2023). "Given the high abundance of collagen in the tumor microenvironment, collagen/LAIR1 signaling in tumor cells plays an important role in downregulating antitumor responses." (PMID 37845206, 2023). "In our work, the range of LAIR-1 expression in both tumor subtypes and cell types shows its prognostic value in human NSCLC." (PMID 36960400, 2023). "Consistent with the finding of tumor compartmentalized AQUA scores, patients with high LAIR-1+/CK+ tumor cell densities showed worse outcomes (HR = 1.5) in both discovery and validation cohorts." (PMID 36960400, 2023). "LAIR‐1 expression also varied statistically in the three immune tumor subtypes, suggesting that LAIR‐1 expression was inextricably linked to the proposed immune subtypes." (PMID 35702880, 2023). "To avoid the interference of mouse LAIR1 during tumor development, we bred the Vav-Cre hLAIR1 transgenic mice in the mLAIR1-/- background." (PMID 36211388, 2022).
tumor (continued). "Here we report the development of specific antagonistic anti-LAIR1 monoclonal antibodies and studied the effects of LAIR1 blockade on the anti-tumor immune functions." (PMID 36211388, 2022). "The soluble form of LAIR-1 (LAIR-2) blocks the detrimental LAIR-1-mediated inhibition in tumor treatment." (PMID 35562585, 2022). "In this study, we report the generation of anti-LAIR1 humanized antibodies, and focused on studying the function of h219, an antagonist antibody, in anti-tumor immune responses." (PMID 36211388, 2022). "The inhibitory role of LAIR1 in immune regulation has been well documented, but its function during tumorigenesis and tumor progression remains contradictory." (PMID 36555775, 2022). "It has been observed that LAIR-1 expression is normally elevated in immune cells; however, tumor cells hijack this immune regulatory system to avoid the “anti-cancer immune response”." (PMID 36293412, 2022). "Because the only cells that expressed LAIR1 in these mice were human immune cells, our result suggests that the anti-tumor effect of the anti-LAIR1 was from inhibiting LAIR1 signaling in the human immune cells." (PMID 36211388, 2022). "Here we report our development of an anti-LAIR1 antagonist antibody that shows anti-tumor immune activation activity." (PMID 36211388, 2022). "In RCC tumor tissue, LAIR1 was observed as significantly upregulated compared to normal renal tissue." (PMID 36555775, 2022). "Together, we demonstrate that the anti-LAIR1 antagonist antibody inhibited tumor development in mice." (PMID 36211388, 2022). "It has recently been reported that collagen density can regulate the activity of tumor-infiltrating T cells through the collagen receptor LAIR-1 [17, 18,]." (PMID 34782761, 2021). "Previously, we showed that LAIR-2-Fc can revert collagen-induced LAIR-1 mediated immunosuppression, resulting in decreased tumor outgrowth in humanized mouse models." (PMID 34691040, 2021). "LAIR-1 tumoral mRNA expression most likely originates from immune cell infiltrate in the tumor, as it correlates with CD45 tumoral mRNA expression." (PMID 34691040, 2021). "A cross section of tumor types was selected from the TCGA analyses of collagen, LAIR-1 and LAIR-2 mRNA expression and/or survival analyses." (PMID 34121658, 2021). "Further studies are needed to elucidate the role of LAIR-1 in other cancer models and its role in modulating anti-tumor immunity." (PMID 34956223, 2021). "Blockade of LAIR-1 has also been shown to increase the number of tumor-infiltrating CD4+ and CD8+ T cells and enhance the efficacy of anti-PD-L1 treatment in humanized murine xenograft models of several cancers, including colon- and pancreatic cancer." (PMID 34956223, 2021). "In the present study, we found that expressions of FTL and FTH1 correlated positively with levels of the immune checkpoint proteins TIM-3 and LAIR1, both of which can suppress tumor immunity." (PMID 33864445, 2021). "By stratifying patients for high- and low-quantile LAIR-1 mRNA expression, we observed that patients with high LAIR-1 mRNA expression had lower survival probability in four tumor types (Source code 4)." (PMID 34121658, 2021). "Increasing evidence indicates that a high-density collagen matrix reduces CD8+ T cell abundance and that tumor-expressed collagens can suppress the immune response via the collagen receptor LAIR-1 [35, 36,]." (PMID 34782761, 2021). "Our analyses of TCGA datasets show that cancer patients with high tumor mRNA expression of MMPs, collagen I and LAIR-1 have worse overall survival." (PMID 34691040, 2021). "A unique set of tumor types emerged that overlapped with those with significant increased LAIR-1 expression, but only partially with the tumor types in that of the total collagen overall survival analysis." (PMID 34121658, 2021).
tumor (continued). "LAIR-1 strong association with c-MYC and Cdc42, as we observed in our study, and the concomitant high expression of LAIR-1 in these tumours, suggest that these tumours are highly proliferative and are linked with poor prognosis." (PMID 33396670, 2020). "LAIR-1 expression was significantly higher in patients with T2 stage OS tumor than in those with T1 stage OS tumor (P = 0.006)." (PMID 32563267, 2020). "Bcl-2 markedly decreased, leading to a dramatic increase in the Bax/Bcl-2 ratio in LAIR-1 overexpression tumor samples, while the expression levels of ki-67 and PCNA remained unchanged." (PMID 32628130, 2020). "The findings of our study demonstrated that LAIR-1 are overexpressed in human OS tissues and that LAIR-1 expression is significantly higher in the T2 stage OS tumor than in the T1 stage OS tumors." (PMID 32563267, 2020). "When LAIR-1 binds to its ligands, immune function in the tumor microenvironment is lost, and T cell function and the immune responses of antigen-presenting cells are reduced." (PMID 33147797, 2020). "LAIR-1 IHC expression predominantly shows cytoplasmic staining with occasional membranous staining in a few tumour cells." (PMID 33396670, 2020). "Siglec-7, IRp60 and LAIR-1 are rarely discussed in most reviews on immune checkpoints in NK cell context, however, they represent relevant receptors to target in anti-tumor immunotherapies." (PMID 33013909, 2020). "In addition, the cancer stemness score (RNAss) was negatively correlated with LAIR1 and VAMP8 and positively correlated with CKAP2L and SOX6, indicating that these hub genes are linked to tumor stemness-related characteristics." (PMID 41614933, 2026). "Along these lines, it has been shown that LAIR1 is associated with stroma and strongly expressed in several human tumors, mainly on myeloid CD68+ SMA+ cells with suppressive functional features in human tumor and tumor murine models." (PMID 40563506, 2025). "Next, we evaluated the effect of anti-Lair1 antibody on the antitumor response using tumor models." (PMID 40591413, 2025). "In several solid tumors, elevated LAIR2 levels have been associated with improved prognosis and overall survival, suggesting a role for LAIR2 as a potential therapeutic agent that may reduce LAIR1-mediated immune suppression in the tumor microenvironment." (PMID 40563506, 2025). "Enhanced antitumor responses were observed when Lair1–/– or anti-Lair1 antibody was used alone or in combination with CAR T cells or when the 3-in-1 CAR T cells were used solely in tumor models resistant to chemotherapy–radiation–programmed cell death protein 1 (PD-1) blockade." (PMID 40591413, 2025). "The finding of LAIR1 expression on hematological malignancies, but also on some solid tumors, could open a rationale for the targeting of this molecule to treat neoplasia, either alone or in combination with other therapeutic options." (PMID 40563506, 2025). "Additionally, lower LAIR1 levels in this group enhance macrophage activity and inflammatory responses, thereby reducing tumor progression." (PMID 41153362, 2025). "To explore the role of LAIR1 in tumor progression, we created a Lair1–/– GBM TB mouse model." (PMID 40591413, 2025). "This hypothesis was supported by the finding that Lair1–/– tumor-bearing mice exhibited a decrease in intratumoral M2-like TAMs, while the total number of MΦ remained unchanged." (PMID 40591413, 2025). "Next, we sought to understand how the tumor immune landscape was affected by Lair1 knockout." (PMID 40591413, 2025). "However, the blocking of the LAIR1-mediated signal in tumor-infiltrating lymphocytes should elicit a strong antitumor immune response in both T and NK cells." (PMID 40563506, 2025). "Anti-Lair1 antibody enhances the antitumor response in tumor models." (PMID 40591413, 2025).